Y_RNA (Y RNA )
Gene: Miscellaneous RNA gene on chromosome 11 (118,836,010 to 118,836,111, forward strand). Ensembl gene ENSG00000201535.
Homologues: Orthologues: chimpanzee Y_RNA (98% identical), macaque Y_RNA (92% identical), pig Y_RNA (75% identical). Paralogues in human: Y_RNA (88% identical), RNY3 (87% identical), Y_RNA (87% identical), RNY3P1 (86% identical), Y_RNA (86% identical), Y_RNA (85% identical), Y_RNA (84% identical), RNY3P11 (83% identical), Y_RNA (83% identical), RNY3P14 (82% identical), RNY3P16 (82% identical), RNY3P2 (82% identical), and 95 more.